ECT2 (epithelial cell transforming 2)
Diseases named in the same sentence as ECT2 in open-access papers (continued):
Sharing a sentence is not in itself a finding about the gene and the disease.
cancer (continued). "ECT2 has been found to be involved in the development of various human cancers." (PMID 34367280, 2021). "It would be interesting to determine, whether the S-phase accumulation phenotype and the AS regulatory pathways (involving ZRANB2, SYF2 and ECT2-Ex5) that we identified, may be related to the cancer stem cell phenotype of Doxo-resistant cells." (PMID 31943118, 2020). "GSEA revealed that high ECT2 expression was enriched for hallmarks of malignant tumors." (PMID 33062405, 2020). "PKC-ζ has been shown to be involved in tumorigenesis, tissue invasion, and cancer progression through the modulation of cell migration machinery, such as Ras Homolog Family Member A (RhoA), Rac Family Small GTPase 1 (Rac1), and Epithelial Cell Transforming 2 (Ect2)." (PMID 32175276, 2020). "It was suggested by Meta‐Analysis that ECT2 was a promising prognostic factor in cancers." (PMID 32592319, 2020). "Specifically, paclitaxel could switch the splicing of ECT2 from the canonical full-length isoform towards the short isoform ECT2-S, which in turn inhibit cancer cell proliferation." (PMID 29706628, 2018). "One of our most robust hits, ECT2 siRNA, had the ability to engage a senescence response enhanced by mutant KRASG13D and therefore shows promise as a target for senescence induction therapy for a range of cancers harbouring this mutation." (PMID 28806777, 2017). "As an oncogene, ECT2 upregulation also has prognostic values in some cancers." (PMID 29088286, 2017). "ECT2 is frequently upregulated in human cancers and acts as an oncogene." (PMID 29088286, 2017). "It would therefore be of interest to determine if the mislocalization of Ect2 and/or Net1 to the cytoplasm could be a potential resistance factor in human cancers to IR or other DNA damaging agents." (PMID 21373644, 2011). "To investigate mRNA expression of ECT2 identified as a cancer-related gene by our microarray analysis, we performed quantitative reverse transcriptase PCR (qRT-PCR) analysis using six OSCC-derived cell lines (HSC-2, HSC-3, HSC-4, H1, Ca9-22, and Sa3) and human normal oral keratinocytes (HNOKs)." (PMID 21124766, 2010). "Moreover, ECT2 has been reported to be overexpressed in a panel of human cancers." (PMID 37106813, 2023). "However, in non-cancer tissue, ECT2 staining was only detected in nuclear." (PMID 36572949, 2022). "It is generally believed that transforming ECT2 variant is not related to human cancers." (PMID 36572949, 2022). "Therefore, we hypothesized that ECT2 and its related genes act in the cell cycle, which in turn affects the proliferation and metastasis of cancer cells." (PMID 35722628, 2022). "Thus, we next sought to investigate whether the splicing switch of ECT2 is indeed involved in the paclitaxel-mediated cancer inhibition." (PMID 29706628, 2018). "Alternative splicing was pervasive, with recurrent high-magnitude events at cancer-relevant loci including GJA1 (SE), NF2 (A3/A5), LIN37 (A5), ECT2 (A3/A5), BCL2L11 (A3), UQCRH (A5), CSE1L (A3), BROX (A3), and multiple ZNFs." (PMID 41952686, 2026). "Overall, these results show how Ect2 and anillin cooperate to mediate RhoA/ROCK/myosin II-dependent mechanoadaptation and invasive cancer progression." (PMID 40571734, 2025). "One noteworthy example is Ect2, an oncogenic guanine nucleotide exchange factor (GEF) overexpressed in diverse cancers." (PMID 38633862, 2024). "In the present study three key genes in UCEC include Endoglin, GNG4 and epithelial cell transforming 2 (ECT2) identified, therefore enhancing our comprehension of UCEC and broadening insights into the prognosis for this cancer type." (PMID 39552710, 2024). "The potential prognostic survival benefits of ANLN and ECT2 reported in our study are supported by Zhang and colleagues’ evaluation of the carcinogenic roles of ANLN in various types of cancers via a pan-cancer analysis utilizing the TCGA-GTEx database." (PMID 38785827, 2024).
cancer (continued). "Genes related to cancer stem cells and tumorigenesis, such as KPNA2, ECT2, ERCC6L and TUBB4B, and the cell-cycle regulators DLGAP5, KIF2C and BUB3 were also significantly upregulated in the CSPG+ group, and clustered well within the same area." (PMID 38251863, 2024). "The cell cycle, proteasome, and pathways in cancer were enriched in the high-COL17A1 and ECT2 groups." (PMID 35722628, 2022). "A recent analysis of TCGA data identified significantly higher expression of the RhoGEFs Trio, Net1, Ect2, Tiam2, Farp1, ARHGEF12 and BCR in primary cancer types compared with normal tissues." (PMID 34196668, 2021). "Several investigators have previously reported the relevance of TRIO, NET1, ECT2 and TIAM2 in cancer metastasis and clinical prognosis." (PMID 32029704, 2020). "The Cancer Genome Atlas (TCGA) data analysis indicated that the gene expression of TRIO, NET1, ECT2, TIAM2, FARP1, ARHGEF12 and BCR in primary cancer was significantly higher than those in normal tissues." (PMID 32029704, 2020). "Together, both studies suggest that ECT2 and DLC1 frequently act together, but in opposite directions, in cancer to increase RhoA activity." (PMID 30278072, 2018). "Strikingly, there is evidence thatANLN, ECT2, PRC1,RACGAP1, ASPM, and PLK1 areupregulated in a variety of human cancers and that their overexpression oftencorrelates with poor outcome (see for example and references therein)." (PMID 21386884, 2011). "The LCM data set shows significant over-expression of ECT2 (FDR 5.00e-4, cancer/normal ratio 1.88) and suggests over-expression of TNFSF10 (FDR 0.014, cancer/normal ratio 1.78)." (PMID 19419571, 2009). "Despite this elevated attention for ECT2 in oncology-related reports, there is no collective study to combine and integrate the expression and oncogenic behavior of ECT2 in a panel of human cancers." (PMID 37106813, 2023). "For example, ASPM, ECT2, AURKA, BIRC5, CENPF, and EZH2 are amplified in several cancers." (PMID 36612203, 2022). "We identified distinct AS events of FMNL3, ZMIZ2, ECT2, PLD2, and DDIT3, which may be involved in cancer cell proliferation, epithelia-mesenchymal transition and actin cytoskeleton organization." (PMID 29706628, 2018). "The differential expression ratio (epithelial cell transforming sequence 2 oncogene—ECT2/ Glyceraldehyde 3-phosphate dehydrogenase—GAPDH) of ECT2 and the number of cancer cells was linearly correlated, as shown by the scatter plot used to confirm the RNA extraction quality (r = 0.97)." (PMID 28362321, 2017). "This region has cancer-related genes (PRKC1 and SOX2) as well as ECT2." (PMID 21124766, 2010). "In addition, the expression and survival of ECT2 and COL17A1 were analyzed in pan-cancer." (PMID 35722628, 2022). "Also, it remains to be tested whether the positive feedback regulation of ECT2 and USP7 is applicable for other types of cancer." (PMID 32929379, 2020).
infection (3 papers, 2012 to 2015). The state of being infected such as from the introduction of a foreign agent such as serum, vaccine, antigenic substance or organism. "Possibly, deletion of ECT2, which is essential for embryonic development and maintenance of the function of uriniferous tubules, caused tubular dysplasia, and when the tubulointerstitial disorder progressed postnatally after an infection, the renal circulation was disturbed." (PMID 22552385, 2012). "Following infection only unc-73(ce362) and ect-2(ku427) significantly decreased the percentage of infected animals with a Dar phenotype, indicating that a subset of Rho signaling pathways are required for the pathogen-induced Dar response." (PMID 22359503, 2012). "We employed real-time PCR to detect 40 GAP and GEF genes and determined that the mRNA levels of SOS1, RasGRP3, Ect2, and Collybistin were increased in HepG2 cells after rAd-ASPP2 infection for 48 and 72 hours." (PMID 25980493, 2015).
benign-tumor (1 paper, 2024). "Given our findings, which suggest that low expression of ANLN and ECT2 are associated with increased overall survival, we validated ANLN and ECT2 expression in both the TCGA PRAD cohort and an AA prostate contralateral benign-tumor-matched cohort." (PMID 38785827, 2024).
gynecological tumors (1 paper, 2025). "Notwithstanding these significant strides, substantial knowledge gaps remain in the exploration of the ECT2 and RhoA/ROCK pathways and their intricate crosstalk mechanisms within gynecological tumors." (PMID 40655948, 2025). "Through comprehensive analysis and summary of the current research results, it is revealed that the ECT2/RhoA/ROCK signaling pathway and related crosstalk pathways play an important role in the occurrence, development, and metastasis of gynecological tumors." (PMID 40655948, 2025).
ECT2 also shares sentences with these, for which no sentence is quoted: breast tumors (3 papers); stomach cancer (3); breast (2); colon cancer (2); non-small cell lung adenocarcinoma (2); Tetralogy of Fallot (2); adenocarcinoma (1); bone tumors (1); colorectal tumor (1); developmental delay (1); epilepsy (1); fibrosis (1); focal segmental glomerulosclerosis (1); head and neck cancer (1); head and neck squamous cell carcinoma (1); human papillomavirus infection (1); invasive breast carcinoma (1); liver cirrhosis (1); melanoma (1); meningioma (1); metastatic tumours (1); ovarian epithelial tumor (1); pancreatic ductal adenocarcinoma (1); serous ovarian cancer (1); soft tissue sarcoma (1); thyroid (1).